STAT3 (signal transducer and activator of transcription 3)
Diseases named in the same sentence as STAT3 in open-access papers (continued):
Sharing a sentence is not in itself a finding about the gene and the disease.
rheumatoid arthritis (continued). "Although there are many strategies for targeting the STAT3 signaling pathway, only indirect inhibitors, such as the JAK and tyrosine kinase inhibitors, have received FDA approval for use against rheumatoid arthritis and myeloproliferative neoplasm." (PMID 32257917, 2019). "In patients with rheumatoid arthritis, FRA1 and JUNB were colocalized with STAT3 in the inflamed synovium." (PMID 29326694, 2017). "This is in line with published data from fibroblast-like synoviocytes isolated from patients with rheumatoid arthritis and stimulated with recombinant OSM, in which OSM increased STAT1, STAT3 and STAT5 expression." (PMID 24710357, 2014). "It has recently been established that SWR could alleviate rheumatoid arthritis by restraining the MAPK and STAT3 signaling pathways, ameliorating HUA by regulating the MAPK and NF-κB signalling pathways." (PMID 40635741, 2025). "In rheumatoid arthritis (RA), adiponectin has been shown to promote the proliferation and differentiation of B cells by inducing the activation of the PI3K/Akt and activator of transcription 3 (STAT3) signaling pathways, exacerbating RA development." (PMID 38813109, 2024). "The authors concluded that LGL clones with STAT3 mutation can be found in a small proportion of acquired BM failure syndromes, such as AA and MDS, and this mechanism might also be involved in associated autoimmune diseases, including rheumatoid arthritis (RA)." (PMID 38610985, 2024). "It is proposed that the ability of YSTB to slow the progression of rheumatoid arthritis may be related to modulating the JAK/STAT pathway by degrading the phosphorylated expression of JAK2, JAK3, and STAT3 proteins, whereas elevated SOCS3 protein expression." (PMID 38966637, 2024). "Growing evidence supports that downregulation of JAK2 and STAT3 phosphorylation can mitigate inflammation, as seen in conditions such as cerebral ischemic stroke (IS) injury, LPS-induced microglial cell inflammation, atopic dermatitis, and rheumatoid arthritis (RA)." (PMID 39187810, 2024). "For example, it was shown to effectively inhibit Receptor activator of nuclear factor-κB ligand (RANKL) expression by inhibiting the JAK2/STAT3 pathway and upregulating SOCS3 in rheumatoid arthritis fibroblast-like synoviocytes (FLS) stimulated with IL-6/sIL-6R." (PMID 39769302, 2024). "Theophylline is an anti-inflammatory substance, and previous studies have shown that theophylline can reduce the levels of IL-6, COMP, JAK2, STAT3, RANKL, iNOS, and eNOS by modulating the JAK/STAT/RANKL signaling pathway, thereby alleviating the inflammatory response in rheumatoid arthritis." (PMID 37076836, 2023). "In particular, when STAT1, STAT3, and STAT6 are activated as transcription factors by inflammatory cytokines, they can induce the expressions of genes and lead to inflammatory conditions such as asthma, rheumatoid arthritis, and AD." (PMID 38258052, 2023). "Research demonstrates that angiogenesis can be hampered under an environment of inflammation as well as impede the inflammation-induced expression of VEGF in MH7A cell partly through the pathway IL-6/JAK2/STAT3/VEGF, providing new prospects for treating rheumatoid arthritis." (PMID 33499333, 2021). "Furthermore, patients with large granular lymphocytic leukemia caused by somatic STAT3 mutations present with rheumatoid arthritis (RA) four times more often than mutation negative patients." (PMID 30541027, 2019). "PLAG caused a decrease in IL-6 production in the RAW264.7 macrophage cell line and in rheumatoid arthritis–fibroblast-like synoviocytes via the regulation of STAT3 signaling without affecting NF-κB signaling." (PMID 29228558, 2017). "Furthermore, IL-6 family members activate the gp130-JAK-signal transducer and activator of transcription 3 (STAT3) signaling cascade to up-regulate Wnt5a transcription in chronic persistent inflammation and rheumatoid arthritis." (PMID 24278135, 2013).
rheumatoid arthritis (continued). "Furthermore, interleukin (IL)-6 family members activate the gp130-JAK-signal transducer and activator of transcription 3 (STAT3) signaling cascade to up-regulate Wnt5a transcription in chronic persistent inflammation and rheumatoid arthritis." (PMID 22485170, 2012). "Cryptotanshinone induced the apoptosis of fibroblast-like synovial cells in rheumatoid arthritis (RA-FLSs) through the reactive oxygen species-mediated Akt, mitogen-activated protein kinase (MAPK), and STAT3 signaling pathways." (PMID 38542838, 2024). "Moreover, prolactin induces the phosphorylation and activation of the signal transducer and activator of transcription-3 (STAT3), resulting in the downregulation of the osteoclast differentiation induced by proinflammatory cytokines, like IL-1β and IL-6, and rheumatoid arthritis (RA)." (PMID 38338751, 2024). "The co-activation of NF-κB and JAK2/STAT3 induce a massive and sustained production of proinflammatory cytokines, such as IL-6 and IFN-γ, which are critical for the development of inflammatory diseases including rheumatoid arthritis (RA) and multiple sclerosis (MS)." (PMID 35246140, 2022). "Signal transducer and activator of transcription 3 (STAT3) is the key mediator of both chronic inflammation and joint destruction in rheumatoid arthritis (RA)." (PMID 34957061, 2021). "The expression of protein inhibitor of activated STAT3 (PIAS3) showed negative correlation with the level of Th17 in rheumatoid arthritis (RA) patients, and mice model of graft-versus-host disease revealed that PIAS3 upregulates Th17 population and downregulates Treg population." (PMID 30630513, 2019). "Furthermore, clonal deletion of activated T cells was altered and these chronically activated T cells showed persistent IL-6-induced STAT3 and JAK1 phosphorylation indicating that IL-6 signaling in T cells plays a critical role in disease progression of rheumatoid arthritis." (PMID 31694340, 2019). "Compared with healthy people, Tfh cells expression level in rheumatoid arthritis (RA) patients was increased, and Tfh cells proportion was positively correlated with disease activity score in 28 joints (DAS28), phosphorylated STAT3 (pSTAT3) -Tyr705, and plasma IL-6 concentration." (PMID 38051200, 2024). "One limitation is that we have not yet explored the optimal therapeutic dose of EU-Idd for rheumatoid arthritis, and another limitation is that our results have not been verified by using JAK2/STAT3 pathway inhibitor." (PMID 37123081, 2023). "The expression of RANKL, JAK2, STAT3, and SOCS3 proteins was assessed by western blot analysis, real-time PCR and ELISA in IL-6 combined with soluble IL-6 receptor (sIL-6R)-stimulated rheumatoid arthritis (RA)-FLS with or without tacrolimus treatment." (PMID 23406906, 2013). "IL-6, as a pro-inflammatory cytokine, has been proposed to contribute to the progression of rheumatoid arthritis and Crohn's disease, while SOCS3 is a major negative regulator of the IL-6-related cytokine-STAT3 pathway and enhanced expression of SOCS3 inhibits these inflammatory responses." (PMID 33281724, 2020).
autoimmune disease (164 papers, 2009 to 2026). A disorder resulting from loss of function or tissue destruction of an organ or multiple organs, arising from humoral or cellular immune responses of the individual to their own tissue constituents. "Over the past two decades, research has linked persistent STAT3 activation to a wide range of diseases, including bone‐related diseases, cardiovascular diseases, inflammatory diseases, autoimmune disorders, neurodegenerative diseases, and various cancers." (PMID 40166646, 2025). "Signal transducer and activator of transcription 3 (STAT3) is a key transcription factor closely associated with chronic inflammation, autoimmune diseases, and tumor development." (PMID 40733369, 2025). "Clinically, STAT3-mutated patients demonstrate stronger cytotoxic characteristics, a higher incidence of neutropenia, autoimmune diseases, a greater treatment requirement, and diminished overall survival." (PMID 40895526, 2025). "The association of rs3024505(T) with several autoimmune diseases likely arises as a consequence of its contribution to STAT3-mediated IL10 downregulation." (PMID 39337678, 2024). "Increased phosphorylation of STAT3, which is associated with manifestations in autoimmunity and immunodeficiency, has been correlated with multisystem autoimmune disease occurrence in humans." (PMID 38674328, 2024). "A recent study connected germline STAT3 gain-of-function mutations to autoimmune disease through oligoclonal accumulation of effector CD8+ T-cells." (PMID 39497832, 2024). "Consistent with the detection of neutropenia in LGLL patients, STAT3 mutations also appear to be associated with worse clinical course in patients with autoimmune disorders, particularly in RA and Felty syndrome." (PMID 38238319, 2024). "The dysregulation of the JAK2/STAT3 pathway is associated with various cancers and autoimmune diseases." (PMID 38794198, 2024). "STAT3 mutations are also found in a variety of cell types across both autoimmune diseases and hematologic disorders such as myelodysplastic syndrome, aplastic anemia, celiac disease, and multiple sclerosis." (PMID 39497832, 2024). "STAT3 GOF mutations are associated with early-onset multiorgan autoimmune disease, principally manifesting as arthritis and diabetes, as well as primary immunodeficiency that is associated with an increased susceptibility to recurrent severe infections." (PMID 38255152, 2023). "Previous studies have reported that RORγt or STAT3 deficient mice are resistant to autoimmune diseases, and mice treated with FoxP3 displayed enhance Treg function and the alleviation of autoimmune diseases, such as IBD and experimental arthritis." (PMID 35185872, 2022). "In contrast, gain-of-function mutations in STAT3 are not only associated with greatly reduced IgE levels but also with much higher rates of other autoimmune disorders." (PMID 35928809, 2022). "More interesting, recent studies reported germline activating STAT3 led to autoimmune disease, while germline inactivating STAT3 mutations resulted in AD-HIES, emphasizing the critical role of STAT3 in the immune system." (PMID 35345674, 2022). "Functional studies identified that STAT3, a master factor associated with autoimmune diseases, directly regulates both the AI of risk variant and the activity of SE in cultured B cells." (PMID 35188103, 2022). "We included 10 patients with CSUaiTIIb and low levels of IgE and sequenced selected single nucleotide polymorphisms (SNP) in STAT3 associated with common autoimmune diseases." (PMID 35928809, 2022). "The discovered high prevalence of somatic mutations in STAT3 SH2 domain provides opportunities to analyze these mutations directly in autoimmune disease patients’ tissue-infiltrating CD8+ cells." (PMID 36441748, 2022).
autoimmune disease (continued). "We further demonstrate that the resultant allelic imbalanced variant and SE activity are directly controlled by STAT3, a master TF that plays a critical role in B cell development and highly associates with autoimmune diseases." (PMID 35188103, 2022). "Single nucleotide polymorphisms (SNP) in STAT3 have been found to be of relevance in autoimmune diseases." (PMID 35928809, 2022). "Potentially triggered by a chronic persistent stimulus, T-LGLL carries somatic STAT3 mutations in about 30–40% of cases and is often associated with autoimmune disorders." (PMID 33876323, 2021). "STAT3 SNP (rs744166) was associated with multiple sclerosis (MS), whereas the protective haplotype for MS in STAT3 is a risk allele for Crohn’s disease, implying that STAT3 represents a shared risk locus for at least two autoimmune diseases." (PMID 34307193, 2021). "STAT1 and STAT3, which were found to be significantly dampened by P4, have been implicated in the disease pathogenesis of several autoimmune diseases." (PMID 34054852, 2021). "STAT3 gain of function mutation is associated with autoimmune disease, potentially by impairing development of regulatory T cells and promoting activation of T helper type 17 cells." (PMID 33897686, 2021). "Gain-of-function (GOF) mutations in STAT3 are associated with multiorgan autoimmune disorders and immunodeficiency." (PMID 32944025, 2020). "Altogether, this translated into a significantly higher frequency of STAT3-mutated T-LGLL cases requiring therapy (due to the associated-autoimmune disorders)." (PMID 33255665, 2020). "Monogenic activating STAT3 mutations were identified in individuals with a spectrum of early-onset autoimmune disease including juvenile-onset arthritis." (PMID 29915585, 2018). "In this study, we report a novel function of Act1 as a negative regulator in T and B cells via direct inhibition of STAT3, thereby contributing to the development of autoimmune diseases associated with Act1 deficiency." (PMID 30013031, 2018). "The dysregulated inflammation involved in the pathogenesis of autoimmune diseases is associated with induction of a chronic inflammatory response by STAT3." (PMID 27258062, 2016). "STAT3 has a role in the development of Th17 cells, which have been associated with several autoimmune diseases." (PMID 26343524, 2015). "We describe a novel Pro471Arg STAT3 mutation in a patient with multiple autoimmune diseases, causing hyperactivation of the Th17 pathway." (PMID 26343524, 2015). "Mutations in STAT3 have recently been shown to cause autoimmune diseases through increased lymphoproliferation." (PMID 26343524, 2015). "STAT3 activation has been linked to several autoimmune diseases, including systemic lupus erythematosus, a condition arising from uncontrolled humoral immune responses." (PMID 23734190, 2013). "Aberrant STAT3 signaling has been linked to a broad spectrum of diseases, including bone‐related disorders, cardiovascular conditions, inflammatory diseases, autoimmune disorders, neurodegenerative diseases, and various types of cancer." (PMID 40166646, 2025). "Furthermore, phenotypic characteristics of early‐onset multiorgan autoimmunity cased by STAT3 GOF variants overlap with other monogenic autoimmune disorders." (PMID 38404237, 2024). "Variations in the STAT3 gene are associated with autoimmune diseases and cancer." (PMID 39734345, 2024). "Among these SNPs, rs1053005 A/G SNP in the 3′ untranslated region of STAT3 mRNA was identified as a Hyper-IgE recurrent infection syndrome 1 susceptibility locus, which is responsible for many autoimmune disorders such as Grave’s disease and Hashimoto thyroiditis." (PMID 38066785, 2023). "STAT3 is a transcription factor activated by cytokines such as IL-6, IL-10, and growth factors, and is implicated in the activation of Th17 cell responses and autoimmune diseases as well as anti-inflammatory responses." (PMID 36882813, 2023).
autoimmune disease (continued). "Selected single nucleotide polymorphisms in STAT3 associated with common autoimmune diseases." (PMID 35928809, 2022). "Furthermore, the high discovered prevalence of STAT3 somatic mutations makes it feasible to analyze these mutations directly in tissue-infiltrating CD8+ cells in autoimmune diseases." (PMID 36441748, 2022). "Moreover, dysregulated STAT3 signaling has been reported in B cells in autoimmune diseases associated with abnormal GC reaction or plasma cell expansion." (PMID 35359922, 2022). "Mutations in STAT3 can cause lymphoproliferative and autoimmune diseases." (PMID 34394075, 2021). "In humans, lack of functional STAT3 leads to severely impaired Th17 development, as observed in patients with the hyper-IgE syndrome caused by mutations in STAT3 gene, and contrasts with patients with activating germline mutations in STAT3, which cause early-onset multiorgan autoimmune disease." (PMID 33411696, 2021). "Several SNPs within STAT3 locus have been associated to AS and CD, but their impact on Th17 function in these conditions has never been clarified, while different causing SNPs of STAT3 showed to impact Th17 differentiation in other autoimmune diseases." (PMID 34630512, 2021). "In addition, IL-22 induces the expression of proinflammatory cytokines that activate signal transducer and activator of transcription 3 (Stat3), which is associated with autoimmune diseases." (PMID 30159338, 2018). "Moreover, STAT3 is critical in autoimmune disease—any mutation that induces excessive STAT3 activation initiates several autoimmuned is orders." (PMID 27258062, 2016). "The diversity in clinical manifestations of STAT3 mutations suggests that mutations in this gene might underlie more autoimmune disorders, specifically when disease onset occurs at early age." (PMID 26343524, 2015). "Interestingly, similar to our findings, opposing effects of STAT3 variants on different Th17-mediated autoimmune diseases have been reported." (PMID 20454450, 2010). "While STAT3 plays an essential role in homeostasis, its persistent activation has been implicated in the pathogenesis of various diseases, particularly cancer, bone‐related diseases, autoimmune disorders, inflammatory diseases, cardiovascular diseases, and neurodegenerative conditions." (PMID 40166646, 2025). "Dysregulated STAT3 activity, whether through hyperactivation or inactivation, has been implicated in various human diseases, including atherosclerosis, bone‐related disorders, neurological conditions, autoimmune diseases, and cancer." (PMID 40166646, 2025). "If STAT3 is ov2ctivatedated, it may cause cancer or autoimmune diseases." (PMID 35810312, 2022). "Besides, patients with mutations classified as “gain-of-function” in STAT3 gene had an increased Th17 frequency and a diminished number of Tregs, and this dysregulation of the immune system could explain their autoimmune diseases." (PMID 33362761, 2020). "In addition, the inhibitory effect of DDZ on IL-6-induced STAT3 activation may be associated with its potential beneficial application against autoimmune diseases." (PMID 31878046, 2019). "Results showed a STAT3 gene association in MS, which implies a risk for another autoimmune disease in this cohort and has also raised the hypothesis that some genetic variants may be either more easily identified or etiologically more relevant in certain isolated populations." (PMID 25431672, 2014). "Over activation of the JAK/STAT pathway contributes to autoimmune diseases, such as increased IL-6/STAT3 signaling in rheumatoid arthritis." (PMID 40650173, 2025). "This process is mediated by the STAT3-mediated activation of RORγt, a transcriptional factor essential for the pathogenesis of autoimmune disorders." (PMID 41383619, 2025). "We next sought to evaluate ex vivo cytokine secretion as a potential mechanism for autoinflammatory and autoimmune disease presentation in STAT3 GOF patients." (PMID 39836489, 2025).